PAX6 (paired box 6)
Diseases named in the same sentence as PAX6 in open-access papers (continued):
Sharing a sentence is not in itself a finding about the gene and the disease.
aniridia (continued). "In the current study we reported a novel PAX6 deletion resulting in an abnormal PAX6 COOH-terminal extension in the Chinese family affected by aniridia." (PMID 22550392, 2012). "In the present study, we report a genomic microdeletion in the downstream region of PAX6 in a large Chinese family with familial aniridia and other eye anomalies, using microarray-based comparative genomic hybridization (aCGH) techniques." (PMID 21321669, 2011). "Eye development is highly sensitive to Pax6 dose and haploinsufficiency in human PAX6+/− heterozygotes is characterised by aniridia and other ocular abnormalities." (PMID 22220198, 2011). "If the corneal endothelium and/or stroma of PAX6+/− human aniridia patients are affected like the Pax6+/− mice described here, this might have important clinical implications and could underlie some of the abnormal phenotypes associated with aniridia-related keratopathy." (PMID 22220198, 2011). "PAX6+/− heterozygotes suffer from aniridia and aniridia-related keratopathy (ARK), a corneal deterioration that probably involves a limbal epithelial stem cell (LESC) deficiency." (PMID 22220198, 2011). "This study analyzes the coding sequences of PAX6 in two patients with aniridia from successive generations of one Chinese family and one sporadic patient with aniridia." (PMID 22171157, 2011). "Our finding provides further evidence of the existence of the remote 3′ regulatory elements in the downstream region of PAX6 controlling the expression of this gene, if disrupted, leading to aniridia and other eye anomalies." (PMID 21321669, 2011). "Because of the mixed anterior segment anomalies between the two eyes of this patient and the association of Wilm’s tumor in sporadic cases of aniridia, genetic testing was conducted for PITX2, FOXC1, and PAX6." (PMID 21617748, 2011). "While the familial aniridia can be explained by the PAX6 deletion, it is likely other/additional genetic mechanism(s) played a role in the onset and extraordinarily large growth of the subependymoma." (PMID 20500513, 2010). "It is noteworthy that although PAX6 defects elicit congenital aniridia in a dominant hereditary fashion, phenotypes of the eye are sometimes overlooked, especially when the abnormalities are mild and/or de novo gene defects occur." (PMID 20500513, 2010). "Patients with aniridia and neurologic problems were more linked to WAGR syndrome (75% have mental retardation), Gillespie’s syndrome, chromosome anomalies, or PAX6 gene duplication." (PMID 19898691, 2009). "Heterozygous mutations in the paired box gene 6 (PAX6; OMIM 607108), located on human chromosome 11p13, were previously implicated in familial and sporadic aniridia." (PMID 18483559, 2008). "This mutation has been previously observed in a single case with aniridia, cataracts, nystagmus, and corneal dystrophy (Human PAX6 allelic database)." (PMID 18776953, 2008). "A gene that causes aniridia (PAX-6) is located near the WT1 gene on Chromosome 11p13 and deletions encompassing the WT1 and aniridia genes explain the association between aniridia and WT." (PMID 19718304, 2007). "We screened the PAX6 gene by direct sequencing in three groups of patients: those affected by aniridia; those with diverse ocular manifestations; and those with Peters' anomaly." (PMID 17417613, 2007). "This is the first genetic analysis of familial aniridia in Indian populations and contributes to our understanding of the relationship between PAX6 genotype and ocular phenotype." (PMID 16803629, 2006). "The PAX6 gene was cloned during the search for genes underlying the WAGR syndrome (Wilms tumor, aniridia, genitourinary abnormalities and mental retardation; MIM 194072)." (PMID 15918896, 2005). "In most patients with congenital aniridia, there is a PAX6 haploinsufficiency, which seems to be involved in dysfunction of the limbal epithelial stem cell niche and results in a decreased PAX6 mRNA and protein expression in conjunctival and corneal epithelial cells." (PMID 40094891, 2025).
aniridia (continued). "In AAK, the insufficient PAX6 protein amount is also responsible for the severity of the congenital aniridia phenotype, and the severity could be directly correlated with the PAX6 mutational status." (PMID 40493651, 2025). "In congenital aniridia, with PAX6 haploinsufficiency in most of the cases, morphological changes of the corneal epithelium similar to EBMD, Salzmann nodules, and pterygium formation may all be observed." (PMID 40094891, 2025). "PAX6 is a master regulator of eye development and retinal patterning; a mutation to this gene can cause aniridia and other ocular or systemic issues, whilst NFIB is a downstream target of PAX6 that plays a key role in retinal development and photoreceptor differentiation." (PMID 40817596, 2025). "It is known that Wilms tumor/genitourinary malformations and aniridia are caused by deletions of the WT1 and PAX6 genes, respectively, but the causes of intellectual disability and autistic symptoms remain unclear." (PMID 40380139, 2025). "The findings demonstrated that PAX6-knockdown LECs were more sensitive to travoprost than normal LECs, and offer important experimental evidence to develop pharmacological strategies for treating patients with congenital aniridia complicated by glaucoma." (PMID 40828815, 2025). "In congenital aniridia, with PAX6 haploinsufficiency, we could observe deregulated expression of the retinoic acid signaling components ADH7 and ADH1A1 in previous studies." (PMID 40094891, 2025). "Mutations in the PAX genes are associated with congenital human diseases related to eye development and deafness, including Aniridia and Peter’s anomaly (PAX6) and Waardenburg syndrome (PAX3), suggesting that the PAX genes play a central role in the development of the nervous system." (PMID 40002695, 2025). "Mutations in the pax6 gene can cause aniridia, a disorder characterized by absent or underdeveloped iris, nystagmus, foveal hypoplasia, and related complications such as cataracts, glaucoma, and corneal keratopathy." (PMID 39058170, 2024). "Furthermore, some patients with hereditary aniridia will have deletions or chromosomal translocations that disrupt this PAX6 enhancer, highlighting the diversity of genetic variant classes that can cause LOE." (PMID 38436667, 2024). "In addition to PAX6, aniridia-like phenotypes have been observed in patients with rare variants in FOXC1 and PITX2 as well." (PMID 39449022, 2024). "As this study will show, WGS is able, with reasonable sensitivity, to identify causative variants in individuals with a clinical diagnosis of aniridia who have previously, often repeatedly, tested negative for mutations in the coding region of PAX6." (PMID 38050128, 2024). "The Pax6+/– haploinsufficient Sey mouse model on the 129S1/SvImJ and hybrid F1 backgrounds was recently presented as an alternative aniridia model that has a PTC mutation representing the most frequent human aniridia-causing mutation type." (PMID 39625791, 2024). "Taken together, a 517 kb heterozygous deletion containing four annotated genes, DCDC1, DNAJC24, IMMP1L, and ELP4, was identified in this Chinese family with congenital aniridia, suggesting that transcription-regulating elements in the deleted region are required for the expression of PAX6." (PMID 37752489, 2023). "The reduced cone and rod sensitivity seems to be related to a combination of parameters, suggesting that retinal functional changes in PAX6-related aniridia are not limited to the central macular area but also include cone and rod function in the mid periphery." (PMID 37067366, 2023). "Therefore, one of the primary goals of genetic evaluation in patients with aniridia is to exclude PAX6 deletions that extend to the WT1 gene." (PMID 37542296, 2023). "However, except for copy number variations (CNVs), hardly any other chromosomal rearrangements have been reported in patients with congenital aniridia, mainly chromosomal translocations with 11p13 breakpoints affecting PAX6." (PMID 37269011, 2023).
aniridia (continued). "To date, 30 genomic rearrangements downstream of the PAX6 have been reported in the literature to cause aniridia without neurodevelopment disorders." (PMID 37752489, 2023). "Interestingly, HS2 localizes between E180B and SIMO, two well-characterized and highly conserved enhancers for ocular PAX6 expression, which have also been previously involved in the etiopathogenesis of aniridia." (PMID 37269011, 2023). "Congenital aniridia is the most common ocular disorder caused by the PAX6 gene mutations and is characterized by complete absence of the iris." (PMID 36816037, 2023). "We also reviewed the reported microdeletions downstream of PAX6 in patients with aniridia." (PMID 37752489, 2023). "It is worth noting that ataxia is not part of the aniridia phenotype in either patients with heterozygous PAX6 loss-of-function variants or Sey mice." (PMID 37072572, 2023). "Here, we aimed to evaluate whether genetically uncharacterized cases with congenital aniridia would carry hidden balanced SVs affecting PAX6 or its regulatory elements." (PMID 37269011, 2023). "The condition of the tear film and its integrity appear to progressively deteriorate with increasing age and grade of AAK regardless of the type of PAX6 mutation causing the aniridia." (PMID 36517210, 2023). "Therefore, our work confirms the importance of the sequence integrity of PAX6 enhancers in the pathogenesis of aniridia." (PMID 37269011, 2023). "Defects in PAX6 lead to a broad range of clinical phenotypes, with the most common being aniridia." (PMID 37752489, 2023). "Here we report monoallelic missense variants that are absent for gnomAD and result in substitution of Arg51 or, in a single case, Phe52 residues of MAB21L1 in families with severe aniridia [MIM 106210], a phenotype associated with monoallelic mutations in PAX6 [MIM 607108], and/or microphthalmia." (PMID 36413568, 2022). "We report nine individuals from five families with severe aniridia and/or microphthalmia (with no detectable PAX6 mutation) with ultrarare monoallelic missense variants altering the Arg51 codon of MAB21L1." (PMID 36413568, 2022). "Aniridia is a kind of congenital human pan-ocular anomaly, which is related to PAX6 commonly." (PMID 34016071, 2021). "Some deletions located downstream of PAX6 without affecting the coding region are also known to cause aniridia, likely affecting downstream regulatory regions." (PMID 34610801, 2021). "Pathogenic heterozygous variants in PAX6 cause a variety of ocular disorders including microphthalmia (small eye), aniridia (absent iris), cataracts (clouded lens), nystagmus (uncontrolled eye movement) and coloboma (gap in eye structure)." (PMID 33524672, 2021). "In patients with aniridia secondary to mutations only in PAX6, investigations for Wilms tumor are not necessary." (PMID 34065151, 2021). "The PAX6 gene is expressed in a variety of tissues including the central nervous system and pancreas, but is best known as the essential transcription factor for ocular development, and involvement in the ocular disorder aniridia." (PMID 33531684, 2021). "The most common cause of aniridia is pathogenic variants in the PAX6 gene, accounting for up to 90% of cases, with FOXC1, PITX2, and a few other genes explaining some of the remaining cases but still leaving about 5%–10% of aniridia genetically unexplained." (PMID 33973683, 2021). "Congenital PAX6-aniridia is a rare panocular disease resulting from limbal stem cell deficiency." (PMID 34827649, 2021). "Smaller pineal size, lower melatonin secretion, and greater sleep disturbances has also been found in patients with WAGR and isolated aniridia with PAX6 deletions compared to healthy control patients, suggesting that PAX6 is involved in pineal development and circadian regulation." (PMID 34970513, 2021).
aniridia (continued). "Hence, the purpose of our study is to examine the longitudinal natural history of aniridia, with a focus on genotype-phenotype correlations in a large cohort of molecularly confirmed patients with PAX6-related aniridia." (PMID 34101622, 2021). "Furthermore, haploid insufficiency or deletion of the Pax‐6 gene leads to various ocular diseases including aniridia, cataracts, and glaucoma (Glaser, Jepeal, Edwards, Young, & Favor, 1994)." (PMID 32827359, 2020). "PAX6 mutations also cause various non-aniridia phenotypes without iris abnormalities such as microcornea, foveal hypoplasia, keratitis, and optic nerve malformations." (PMID 32080308, 2020). "The Pax6-deficient mouse model of aniridia (Pax6Sey+/−) has been used for topical application of nonsense mutation suppression drugs on adult eyes." (PMID 32111086, 2020). "There were no indications for achromatopsia, PAX6 mutations, aniridia, or prematurity in their electronic patient records, thus we assume that the majority of non-albinism FH in our cohort appeared in isolation." (PMID 31738774, 2019). "The PAX6 (paired box gene 6) gene is the most important gene that leads to congenital aniridia." (PMID 30621664, 2019). "Inversion prone position effects are not only limited to other species, it has also been reported in some human disease conditions, such as aniridia (PAX6), campomelic dysplasia (SOX9), familial adenomatous polyposis (APC) and Saethre-Chotzen syndrome (TWIST1)." (PMID 31191618, 2019). "In some patients with either no PAX6 gene intragenic mutations nor 11p13 genomic rearrangements, mutations in the Pax6 downstream targets are the cause of aniridia." (PMID 29460221, 2018). "For the treatment of aniridia, it is desirable to have TPs for Pax6 expression in the eye." (PMID 30290306, 2018). "In the present study, we evaluated whether the miRNA regulating Pax6 can be therapeutically targeted to restore PAX6 protein levels in islets isolated from a mouse model of aniridia, called the small eye dickie (Pax6SeyDey) mouse." (PMID 30290306, 2018). "The small eye (Sey) mouse is a model of PAX6-aniridia syndrome (aniridia)." (PMID 30258099, 2018). "While aniridia can be sporadic, the mode of inheritance for the familial form is considered autosomal dominant; however, unlike classical autosomal dominance, PAX6 inheritance shows two phenotypes associated with the different genotypic combinations." (PMID 29850208, 2018). "In humans the congenital eye malformation aniridia is characterized by haploinsufficiency for the PAX6 protein, and studying this condition has enabled the identification of large cis-regulatory regions controlling Pax6 expression." (PMID 30007277, 2018). "Haploinsufficiency in the mouse Pax6 gene results in a clinical model of aniridia with iris hypoplasia being prevalent; while modulation of Pitx2 and Foxc1 gene dose results in pupil and drainage structure abnormalities and thus represent experimental models of ARS." (PMID 28250050, 2017). "Similarly, WAGR-array was unable to identify PAX6 defects in nine of our uncharacterized subjects with aniridia." (PMID 28231309, 2017). "Our results underline the clinical importance of performing exhaustive and accurate analysis of chromosomal rearrangements for patients with aniridia, especially newborns and those without defects in PAX6 after diagnostic screening." (PMID 28231309, 2017). "Besides, as the genomic region surrounding PAX6 are also highly covered, with an average resolution of 1.5 kb, WAGR-array also allows accurately identifying and delimiting 3' PAX6 deletions, as demonstrated in three families with sporadic aniridia." (PMID 28231309, 2017). "Moreover, we identified novel microdeletions affecting 3' PAX6 regulatory regions in three families with isolated aniridia." (PMID 28231309, 2017).
aniridia (continued). "Therefore, the PAX6+/− heterozygous null mutations responsible for the haploinsufficiency in humans are characterized by aniridia and other ocular abnormalities due to insufficient dose of Pax6." (PMID 27463523, 2016). "A separate cohort of 173 individuals with non-syndromic aniridia and with no mutation in PAX6 detected were screened for mutations in ITPR1 using the targeted resequencing amplicons." (PMID 27108798, 2016). "We report molecular genetic analysis of 42 affected individuals referred with a diagnosis of aniridia who previously screened as negative for intragenic PAX6 mutations." (PMID 27124303, 2016). "Furthermore, in a recent study of a mouse model with aniridia (pax6 mouse) topical administration of PTC124 inhibited disease progression and even reversed ocular malformations." (PMID 25292197, 2015). "Aniridia, anophthalmia and microphthalmia have been associated with haploinsufficiency of SOX2 while anterior eye defects, including defects of the iris and ciliary body have been associated with haploinsufficiency of PAX6 in humans." (PMID 25111779, 2014). "Mutations affecting the PAX6 gene result in aniridia, a condition characterized by the lack of an iris and other panocular defects." (PMID 25566032, 2014). "Genetic alterations in PAX6 can lead to various ocular malformations including aniridia." (PMID 24349436, 2013). "A decline of ocular surface Pax6 expression has been observed in a number of ocular surface diseases, ranging from immune disorders like Steven’s Johnson syndrome, to genetic defects, like aniridia." (PMID 24143217, 2013). "This study analyzes the coding sequences of PAX6 in two sporadic patients with aniridia." (PMID 22919266, 2012). "Aniridia and related eye anomalies may arise from chromosomal rearrangements that disrupt the region downstream of the PAX6 transcription unit." (PMID 23284961, 2012). "Most, if not all cases with isolated aniridia, can be attributed to mutations in the paired box gene 6 (PAX6)." (PMID 22509105, 2012). "This study aimed to identify novel PAX6 mutations that lead to familial and sporadic aniridia in northeastern China." (PMID 22815628, 2012). "aCGH evaluation should be applied if there is a negative result for the mutation detection of PAX6 in patients with aniridia." (PMID 21321669, 2011). "Future studies with even higher resolution microarrays are needed to further investigate the potential role of genomic copy number variation in classic aniridia patients without PAX6 mutations." (PMID 21423868, 2011). "Mutations leading to complete absence of the PAX6 protein are responsible for aniridia phenotype whereas milder mutations with protein production are associated with other ocular presentations like corectopia, Reiger anomaly, cataract, glaucoma, etc." (PMID 21633710, 2011). "This possibility is supported by recent reports: 1) mutations in the forkhead box C1 gene (FOXC1, OMIM 601090) are associated with aniridia in two families and 2) aniridia in patients with preserved visual function are not related to PAX6 mutations." (PMID 21850189, 2011). "In the current study, we analyze the underlying genotype of classic aniridia in mostly consanguineous patients by PAX6 analysis and, for PAX6-negative cases, by candidate gene sequencing and array genomic copy number variation analysis." (PMID 21423868, 2011). "Although a small percentage of aniridia cases have no detectable PAX6 mutation, to the best of our knowledge no other genotype has been associated with the classic aniridia phenotype." (PMID 21423868, 2011). "Our postulation is based on following evidence: 1) The heterozygous deletion segregated with aniridia in the five affected individuals but not in the unaffected individual, while the exons and splicing regions of PAX6 are apparently free of mutations." (PMID 21321669, 2011).